YWHAZP4 (tyrosine 3-monooxygenase/tryptophan 5-monooxygenase activation protein zeta pseudogene 4)
Gene: Processed pseudogene on chromosome 6 (127,355,756 to 127,356,789, forward strand). Ensembl gene ENSG00000213131.
Diseases named in the same sentence as YWHAZP4 in open-access papers:
YWHAZP4 is named in the same sentence as 5 diseases in open-access papers, as found by Europe PMC text mining. Sharing a sentence is not in itself a finding about the gene and the disease. The quoted sentences say what the papers report.
Intellectual disability (1 paper, 2024). "Several case studies indicate deletions in the chromosomal region containing YWHAZP4 (6q22.33) is linked to intellectual disability." (PMID 38674334, 2024). "Similar to the YWHAZ phenotype, the chromosomal regions harboring YWHAZP4 (6q22.33), YWHAZP5 (10q25.1), YWHAZP6 (9p13.3), YWHAZP8 (Xq13.2), and YWHAZP10 (Xp11.4) are associated with intellectual disability." (PMID 38674334, 2024).
rheumatoid arthritis (1 paper, 2024). A chronic, systemic autoimmune disorder characterized by inflammation in the synovial membranes and articular surfaces. "Similarly, synovial tissue macrophages from patients in remission from rheumatoid arthritis showed the expression of YWHAZP3, YWHAZP4, and YWHAZP10." (PMID 38674334, 2024).
cancer (1 paper, 2022). A tumor composed of atypical neoplastic, often pleomorphic cells that invade other tissues. "However, for the remaining pseudogenes (DDX12P, NCF1C, RP9P, and YWHAZP4), there were no reports on their biological functions in cancers." (PMID 36272991, 2022).
YWHAZP4 also shares sentences with these, for which no sentence is quoted: autoimmune thrombocytopenia (1 paper); juvenile idiopathic arthritis (1).